PRR27 (proline rich 27)
Synonyms: C4orf40
Tractability: Antibody: UniProt places it where antibodies can reach, with high confidence; UniProt predicts a signal peptide or a membrane-spanning region; its Gene Ontology location is reachable by antibodies, with medium confidence.
Gene: Protein-coding gene on chromosome 4 (70,133,616 to 70,176,799, forward strand). Ensembl gene ENSG00000187533.
Subcellular location: Secreted
Gene Ontology:
Cellular component: extracellular exosome; extracellular region
Genetic constraint (gnomAD): Loss-of-function variants: 7 observed, 10.5 expected, observed/expected ratio (o/e) 0.67, 90% interval 0.38 to 1.25. The upper end of that interval is the gene's LOEUF score, 1.25, which puts it in group 5 of 6, group 1 being the genes least tolerant of losing a copy. Missense variants: 243 observed, 248.74 expected, observed/expected ratio (o/e) 0.98, 90% interval 0.88 to 1.09. Synonymous variants: 92 observed, 92.5 expected, observed/expected ratio (o/e) 0.99, 90% interval 0.84 to 1.18.
Homologues: Orthologues: chimpanzee PRR27 (97% identical), macaque PRR27 (77% identical), mouse Prr27 (42% identical), dog PRR27 (35% identical).